HTN3 (histatin 3)
Description:
Histatins are cationic and histidine-rich peptides mainly found in the saliva of higher primates. They are considered to be major precursors of the protective proteinaceous structure on tooth surfaces (enamel pellicle). Hsts can be divided into two major groups according to their biological functions: antimicrobial Hsts (e.g. Hst 5/HTN3) and cell-activating Hsts (e.g. Hst 1/HTN1, Hst 2/HTN1 and Hst 3/HTN3). [Histatin-3]: Histatin 3 (Hst 3) is mostly involved in cell migration and wound healing in the oral cavity. Also stimulates cell proliferation after binding to heat shock protein HSC70, which enhances HSC70-CDKN1B complex formation and subsequent ubiquitination during G1/S transition. Also displays antifungal activity against pathogenic yeast Candida albicans, however with less effectiveness than Hst 5. [His3-(20-43)-peptide]: Histatin 5 (Hst 5), a fragment of Hst 3, is the major histatin exhibiting antifungal and antibacterial activities. It is effective against pathogenic yeast C.albicans, C.neoformans, C.glabrata and S.cerevisiae as well as ESKAPE bacterial pathogens. Secreted Hst 5 mediates a multi-step intracellular mechanism of action against the pathogen. Depending on peptide concentration and pathogen, uptake across the membrane can occur through transporters, direct interaction with plasma membrane and/or receptor-mediated endocytosis. Binds C.albicans cell wall proteins SSA1 and SSA2 and glycans in an energy-independent manner, then is taken up by the cells through fungal polyamine transporters DUR3 and DUR31 in an energy-dependent manner. Internalized Hst5 is then targeted to the energized mitochondrion to induce reactive oxygen species (ROS) formation and subsequent release of intracellular non-lytic ATP which ultimately leads to fungal cell death. In addition, inhibits C.albicans TRK1 potassium-transporter which causes exudation of intracellular K(+), generating an osmotic imbalance leading to delayed membrane lysis and cell death. Also acts as a potent inhibitor of bacterial proteases such as Lys-gingipain and Arg-gingipain (rgpB) from P.gingivalis as well as human metalloproteases MMP2 and MMP9. The binding of metals such as zinc, copper or nickel with Hst 5 results in the protection of the enamel and antimicrobial activities such as the inhibition of microbial growth by decreasing the metal concentration, the formation of ROS commonly associated with redox-active metals, the induction of membrane disruption mediated by zinc binding. Also involved in coating oral surfaces in the form of a salivary film which reduces colonization by C.albicans on epithelial cell surfaces. Secreted Hst 5 can also internalize mammalian epithelial cells and target the mitochondria although it does not exert cytotoxic effects in these cells. In contrast with Hst 3, not able to promote wound healing in mammalian host cells.
Synonyms: Hst 3; HIS2; HTN2; HTN5; PB
Tractability: Antibody: UniProt places it where antibodies can reach, with high confidence; its Gene Ontology location is reachable by antibodies, with high confidence; UniProt predicts a signal peptide or a membrane-spanning region.
Gene: Protein-coding gene on chromosome 4 (70,028,455 to 70,036,538, forward strand). Ensembl gene ENSG00000205649.
Subcellular location: Secreted; Secreted (His3-(20-43)-peptide); Mitochondrion
Pathways (Reactome):
Immune System: Antimicrobial peptides
Gene Ontology:
Molecular function: molecular adaptor activity; protein binding
Biological process: positive regulation of fibroblast proliferation; positive regulation of wound healing; antimicrobial humoral immune response mediated by antimicrobial peptide; defense response to bacterium; killing of cells of another organism
Cellular component: extracellular region; mitochondrion
Homologues: Orthologues: chimpanzee HTN3 (98% identical). Paralogues in human: HTN1 (84% identical), STATH (39% identical).
Diseases named in the same sentence as HTN3 in open-access papers:
HTN3 is named in the same sentence as 22 diseases in open-access papers, as found by Europe PMC text mining. Sharing a sentence is not in itself a finding about the gene and the disease. The quoted sentences say what the papers report.
periodontitis (3 papers, 2022 to 2025). An acute or chronic inflammatory process that affects the tissues that surround and support the teeth. "Interestingly, our report shows that pregnant women with obesity and periodontitis expressed higher levels of Histatin-3 and Metalloproteinase inhibitor 1 (MMP1), with the latter being a protein uniquely expressed in OP." (PMID 36355174, 2022).
COVID-19 (2 papers, 2024 to 2026). A disease caused by infection with severe acute respiratory syndrome coronavirus 2. "The observed correlations between histatin-3 and ferritin, D-dimer, and albumin further suggest that histatin-3 may be linked to acute-phase and inflammatory responses during COVID-19." (PMID 42267407, 2026). "Bulk RNA-sequencing data from infected parotid glands tissue from deceased COVID-19 patients and uninfected control tissue demonstrated significantly reduced expression of histatin genes (HTN1, HTN3) (>100-fold)." (PMID 39666753, 2024). "Unexpectedly, patients with severe COVID-19, all of whom were receiving corticosteroids, did not exhibit further histatin reductions; their levels were comparable to controls and significantly higher than the mild group (histatin-3 p = 0.016; histatin-5 p = 0.028)." (PMID 42267407, 2026).
pneumonia (1 paper, 2026). An acute, acute and chronic, or chronic inflammation focally or diffusely affecting the lung parenchyma, caused by an infection in one or both of the lungs (by bacteria, viruses, fungi, or mycoplasma.). "SARS-CoV-2 infection without pneumonia was associated with significantly lower serum histatin-3 and histatin-5 levels." (PMID 42267407, 2026).
tumor (2 papers, 2023 to 2024). "In the case of histatin 1 and histatin 3, we could identify only one peptide belonging to those proteins in one extract sample from tumor tissue; however, we suspect that such identification was caused by the imperfect separation of healthy tissue from tumor." (PMID 39201484, 2024). "no peptides derived from four saliva-specific proteins (SATH, SMR3B, HTN1, HTN3) were identified in extracts from tumor tissue." (PMID 39201484, 2024). "The lack of identification of peptides from proteins STATH, SMR3B, HTN1, and HTN3 in extracts from tumor tissues may suggest that there is a complete suppression of the production of these proteins in tumor tissues." (PMID 39201484, 2024). "A prognostic index for tumor samples could be calculated by the formula: IRGPI = (HTN3 expression * 0.096) + (CTSG expression * −0.152) + (MAPT expression * 0.122) + (CCL28 expression * −0.094) + (PTX3 expression * 0.138) + (SEMA3G expression * −0.140) + (USP2 expression * 0.107)." (PMID 36845378, 2023). "The surprising result was that extracts from tumor tissue did not contain peptides derived from salivary gland-specific proteins (STATH, SMR3B, HTN1, HTN3)." (PMID 39201484, 2024). "However, regardless of the tumor type, the effect is the same: a lack of occurrence of peptides derived from proteins STATH, SMR3B, HTN1, and HTN3." (PMID 39201484, 2024). "Extracts derived from tumor tissue do not contain peptides derived from statherin (STATH) and three other proteins: submaxillary gland androgen-regulated protein 3b (SMR3B), histatin 1 (HTN1), and histatin 3 (HTN3)." (PMID 39201484, 2024).
HTN3 also shares sentences with these, for which no sentence is quoted: oral candidiasis (8 papers); infection (5); Candida infection (3); dental caries (3); gingivitis (2); Acinic cell carcinoma (1); AIDS (1); cancer (1); co-infection (1); denture stomatitis (1); Down syndrome (1); malaria (1); nosocomial infection (1); Obesity (1); Opportunistic infection (1); oral squamous cell carcinoma (1); periodontal disease (1); vaginal candidiasis (1).